RPL23AP7 (ribosomal protein L23a pseudogene 7 )
Synonyms: RPL23AL1; RPL23A_6_267; bA395L14.9
Gene: Long non-coding RNA gene on chromosome 2 (113,581,892 to 113,656,309, reverse strand). Ensembl gene ENSG00000293106.
Diseases named in the same sentence as RPL23AP7 in open-access papers:
RPL23AP7 is named in the same sentence as 1 disease in open-access papers, as found by Europe PMC text mining. Sharing a sentence is not in itself a finding about the gene and the disease. The quoted sentences say what the papers report.
tumor (1 paper, 2025). "Of the nine basal‐like‐associated cfRNA markers, five (PTTG2, RPL23AP7, UTS2, KDELC1, and DEGS1) were found to be overexpressed in basal‐like tumor tissue compared with tumors of the classical subtype within the HD tissue cohort." (PMID 39478658, 2025).